CROCCP2 (CROCC pseudogene 2)
Synonyms: MGC12760; formerly CROCCL1
Gene: Transcribed unprocessed pseudogene on chromosome 1 (16,618,969 to 16,657,232, reverse strand). Ensembl gene ENSG00000215908.
Diseases named in the same sentence as CROCCP2 in open-access papers:
CROCCP2 is named in the same sentence as 6 diseases in open-access papers, as found by Europe PMC text mining. Sharing a sentence is not in itself a finding about the gene and the disease.
CROCCP2 shares sentences with these, for which no sentence is quoted: cancer (3 papers); basal cell carcinoma (1); breast carcinoma (1); non-alcoholic fatty liver disease (1); non-small cell lung carcinoma (1); small cell lung carcinoma (1).